LINC00993 (long independently transcribed non-coding RNA 993)
Synonyms: TCONS_l2_00002973
Gene: Transcribed unprocessed pseudogene on chromosome 10 (37,248,118 to 37,315,801, forward strand). Ensembl gene ENSG00000235687.
Diseases named in the same sentence as LINC00993 in open-access papers:
LINC00993 is named in the same sentence as 3 diseases in open-access papers, as found by Europe PMC text mining. Sharing a sentence is not in itself a finding about the gene and the disease. The quoted sentences say what the papers report.
breast carcinoma (2 papers, 2015 to 2019). "Here, we created the needed two groups by separating 1,096 breast cancer samples according to LINC00993 expression." (PMID 31921620, 2019). "In conclusion, LINC00993 is a breast-specific lincRNA, which was downregulated in breast cancer, especially in TNBC." (PMID 31921620, 2019). "In this study, we explored the expression pattern of LINC00993 in clinical breast cancer samples and in The Cancer Genome Atlas (TCGA)." (PMID 31921620, 2019). "Subgroup analysis showed that LINC00993 was downregulated in breast cancer tissues when compared to its paired peritumor tissues in TNBC group (n = 25, p < 0.001)." (PMID 31921620, 2019). "Taken all these results together, LINC00993 was breast-specific and was identified with a tumor suppressive feature and with prognostic value, suggesting that controlling LINC00993 level may be helpful for breast cancer treatment." (PMID 31921620, 2019). "We also studied the function of LINC00993 in breast cancer cells both in vitro and in vivo." (PMID 31921620, 2019). "We proved that LINC00993 was largely downregulated in breast cancer, especially in TNBC." (PMID 31921620, 2019). "LINC00993 was found to be breast-specific and was downregulated in breast cancer." (PMID 31921620, 2019). "Next, we intended to explore the function of LINC00993 in breast cancer." (PMID 31921620, 2019). "Our results suggest that LINC00993 may serve as a tumor suppressor in breast cancer." (PMID 31921620, 2019). "Our results suggest that controlling LINC00993 level may be beneficial for breast cancer treatment." (PMID 31921620, 2019). "However, the role of LINC00993 in breast cancer is totally unknown." (PMID 31921620, 2019). "Noteworthy, the CM1 list revealed a set of probes for which little literature exists in relation to breast cancer subtypes: CDCA5, CCL15, COL17A1, GLYATL2, ROPN1, LINC00993 and C6orf211." (PMID 26132585, 2015). "Our results indicated that LINC00993 was strongly downregulated in TNBC, and its expression in breast cancer might serve as a prognostic biomarker." (PMID 31921620, 2019).
cancer (2 papers, 2019 to 2020). A tumor composed of atypical neoplastic, often pleomorphic cells that invade other tissues. "Regarding the up-regulated lncRNAs, only a low number of them have been previously implicated in cancer, such as the up-regulated CASC15, LINC00662, LINC01272, LINC00857, LINC00092, LINC00673 and the down-regulated LINC00657, LINC01087 and LINC00993." (PMID 32753692, 2020). "LINC00993 showed the potential to be a novel cancer therapeutic target." (PMID 31921620, 2019).
tumor (2 papers, 2018 to 2019). "The results showed that ectopic expression of LINC00993 in MBA-MD-231 xenografts inhibited tumor growth, thus LINC00993 played a tumor suppressor role in TNBC in vivo." (PMID 31921620, 2019). "About 2 weeks after plantation with tumor size at ~100 mm3, the mice were intratumorally injected with Ad-LINC00993, Ad-RFP, or PBS." (PMID 31921620, 2019). "Paired tumor and peritumor samples were extracted, and LINC00993 was found markedly downregulated in basal-like group compared to that in Normal group (n = 20, p = 0.007)." (PMID 31921620, 2019).